GKN1 (gastrokine 1)
Diseases named in the same sentence as GKN1 in open-access papers (continued):
Sharing a sentence is not in itself a finding about the gene and the disease.
Obesity (3 papers, 2021 to 2023). Accumulation of substantial excess body fat. "The fact that GKN1 modifies the microbiota to modulate obesity is relevant as obesity is a well-recognized risk factor for CVDs." (PMID 36317116, 2022). "In a recent study using a GKN1−/− mouse model, it was reported that GKN1 indirectly mediates obesity through its effects on the gut microbiota." (PMID 36317116, 2022). "GKN1−/− mice exhibited an altered gut microbiota with significant reduced prevalence of Firmicutes, which was translated in resistance to diet induced obesity in comparison to wild type mice." (PMID 36317116, 2022). "Since GKN1 is made exclusively in the stomach these findings identify an additional new mechanism for the regulation of diet-induced obesity by the stomach." (PMID 33947892, 2021). "GKN1 is highly conserved across evolution, suggesting that a similar role for GKN1 (and thus the stomach) in human obesity is possible." (PMID 33947892, 2021). "To test this we generated GKN1−/− mice and assessed their body composition and sensitivity to diet-induced obesity." (PMID 33947892, 2021). "An association of NSAID use and BMI has not been reported, but high dose salicylates can result in lower serum insulin and glucose in diet induced obesity models, which phenocopies the insulin and glucose profile of GKN1−/− mice." (PMID 33947892, 2021). "We examined whether GKN1 plays a role in the development of obesity and regulation of the gut microbiome." (PMID 33947892, 2021). "There are no described human patients with GKN1 deficiency or notable genetic associations of GKN1 with obesity." (PMID 33947892, 2021). "Whether suppression of GKN1 by salicylates plays a role in the reversal of diet- and obesity-related insulin resistance remains to be determined." (PMID 33947892, 2021). "Thus GKN1−/− mice are resistant to HFD-diet induced obesity and hepatic steatosis." (PMID 33947892, 2021). "Lastly, agents that suppress GKN1 expression or block its actions in the gut may have the potential to prevent diet-induced obesity, improving quality of life and reducing the burdens of obesity on health care." (PMID 33947892, 2021). "Thus GKN1−/− mice have an altered small bowel microbiome, which may contribute to resistance to diet induced obesity." (PMID 33947892, 2021). "GKN1 may contribute to the effects of the stomach on the microbiome and obesity." (PMID 33947892, 2021). "Gastrokine-1 (GKN1), a member of the gastrokine family, is an anti-amyloid secreted by the stomach, has mitogenic activity, actively acts in protecting the integrity of the gastric mucosal epithelium and regulates diet-induced obesity." (PMID 37808112, 2023). "The major conclusion and most notable finding of this study is that the absence of GKN1, a secreted, stomach-specific, anti-amyloidogenic protein, protects from diet-induced obesity." (PMID 33947892, 2021).
gastric adenocarcinoma (2 papers, 2006 to 2023). "(AMP-18), GKN1, and trefoil factor interactions(z) (TFIZ), was demonstrated to be dramatically down-regulated or absent in the gastric adenocarcinoma patients in this study." (PMID 17187689, 2006).
gastritis (2 papers, 2017 to 2020). Inflammation of the stomach. "Previous investigations revealed no CpG hyper-methylation of the GKN1 promoter in GC tissues and altered GKN1 expression associated with the severity of gastritis and DNA methylation in non-neoplastic gastric mucosa." (PMID 28129645, 2017). "However, the precise relationship between gastritis and GKN1 has not been evaluated." (PMID 28129645, 2017).
Atrophy (1 paper, 2023). Any weakening or degeneration, especially through lack of use. "In addition, another study indicated that serum GKN1 concentrations discriminated healthy individuals with normal stomach and subjects with atrophy without and with intestinal metaplasia (IM) from GC patients with AUCs of 1.0000, 1.0000, and 0.9964, respectively." (PMID 35066729, 2023).
breast carcinoma (1 paper, 2009). "In the BRICHOS region of GKN1, E104T is associated with breast cancer and is conserved to lysine in all other species (except asparagine in cow, and glutamine in mouse and rat)." (PMID 19747390, 2009).
Chagas disease (1 paper, 2025). A parasitic infection caused by Trypanosoma cruzi. "Since there was no increase in the abundance of this protein in control animals, GKN1 could serve as a potential biomarker for oral Chagas disease." (PMID 41471915, 2025).
chronic pancreatitis (1 paper, 2022). A chronic inflammatory process causing damage and fibrosis of the pancreatic parenchyma. "Thus, GKN1 may potentially serve as early biomarkers to suggest predisposition to PDAC or to distinguish between benign and malignant processes, which may provide clinical benefit to some patients, e.g., as surveillance measure for patients with hereditary pancreatic cancer or chronic pancreatitis." (PMID 35082384, 2022).
colorectal carcinoma (1 paper, 2023). A malignant epithelial neoplasm that arises from the colon or rectum and invades through the muscularis mucosa into the submucosa. "Also, serum GKN1 levels in patients with GC yielded AUCs of 0.9938 and 0.9987 distinguishing patients with hepatocellular and colorectal carcinomas from GC patients." (PMID 35066729, 2023).
cyst (1 paper, 2022). A sac-like closed membranous structure that may be empty or contain fluid or amorphous material. "In an exploratory cohort of 24 patients, GKN1 was identified in the cyst fluid of four patients." (PMID 35082384, 2022).
dementia (1 paper, 2009). Loss of intellectual abilities interfering with an individual's social and occupational functions. "There are 8 known families; the cancer associated GKN1, GKN2 and LECT1, the three dementia associated ITM2 families, the respiratory disease associated proSP-C, and TNMD." (PMID 19747390, 2009).
diabetes (1 paper, 2021). "Thus, the lean phenotype of GKN1−/− mice does not appear to be associated with reduced food intake, malabsorption of fat or calories, diabetes, elevated body temperature, increased locomotor activity or increased thermogenic fat." (PMID 33947892, 2021). "We next examined whether GKN1−/− mice might be less fat due to diabetes." (PMID 33947892, 2021).
hereditary pancreatic cancer (1 paper, 2022). "Panc-02 (pancreatic cancer cells of mouse origin) were genetically modified to express GKN1 for further in vitro and in vivo analysis." (PMID 35082384, 2022). "Mechanistically, we noted that GKN1 and GKN2 prevent pancreatic cancer development via different modes of action." (PMID 35082384, 2022). "Therefore, we examined p16 and p21 mRNA transcripts in Panc-02 pancreatic cancer cells, treated with conditioned media with and without GKN1." (PMID 35082384, 2022).
Hypertension (1 paper, 2023). The presence of chronic increased pressure in the systemic arterial system. "Still, an increased expression of SVEP1, NRP1, RNASE1, QSOX1, and GKN1, along with decreased expression of XYLT2, CFH, LEP, and CETP serum levels were found in patients with hypertension." (PMID 37792298, 2023).
latent infection (1 paper, 2014). "To test the effect of EBV latent infection on GKN1 and GKN2 expression, we generated an AGS cell line containing EBV B95.8 bacmid." (PMID 24460791, 2014). "We next asked whether GKN1 or GKN2 mRNA levels were affected by EBV latent infection in AGS cells by comparing RT-qPCR expression levels in AGS relative to AGS-EBV cells." (PMID 24460791, 2014). "We then showed that Aza-treatment led to the increase expression of GKN1 and GKN2, and that EBV latent infection inhibits Aza activation of GKN2." (PMID 24460791, 2014).
lung adenocarcinoma (1 paper, 2023). A carcinoma that arises from the lung and is characterized by the presence of malignant glandular epithelial cells. "In addition, keratin 14 is correlated with nodal metastasis and unfavorable prognosis in human lung adenocarcinoma via Gkn1 induction." (PMID 36949761, 2023).
mucinous tumors (1 paper, 2021). "Gastric proteins HNF4α and GKN1 were increased in mucinous tumors as previously reported." (PMID 33439550, 2021).
pancreatic adenocarcinoma (1 paper, 2023). "Compared with normal tissues, the expression levels of MET, DYNLL2, CDK1, TNFSF10, PIP5K1C, MSLN, and GKN1 were significantly increased in pancreatic adenocarcinoma cells (p < 0.05)." (PMID 37370756, 2023). "At present, there is no report that MSLN and GKN1 are prognostic risk genes for pancreatic adenocarcinoma." (PMID 37370756, 2023). "We identified seven prognostic genes (MET, DYNLL2, CDK1, TNFSF10, PIP5K1C, MSLN, GKN1) and validated that their related proteins, such as EGFR and MMP2, have a significant impact on the prognosis of pancreatic adenocarcinoma." (PMID 37370756, 2023).
tumor (26 papers, 2004 to 2025). "Several recent studies have described anti-proliferative and anti-invasive activity for GKN1 in gastric epithelial cells, which, together with its frequent expression loss in cancer, suggests it functions as tumor suppressor specific to gastric epithelium." (PMID 24460791, 2014). "Furthermore, loss of GKN1 had an impact on tumor stroma leading to the development of a denser and highly collagen rich stroma." (PMID 35082384, 2022). "An immunofluorescent staining assay was conducted to assess cell apoptosis and GKN1 expression in tumor tissue." (PMID 39524138, 2024). "A significant reduction in tumor volume and tumor weight was observed in exosomes containing GKN1‐treated nude mice." (PMID 39524138, 2024). "Overall, these observations support the notion that GKN1 inhibits the transition from low-grade PanIN to high-grade PanINs; thus, acting as tumor suppressor." (PMID 35082384, 2022). "To further investigate effects of gastrokine proteins on tumor growth, we generated GKN1 overexpressing Panc-02 cells." (PMID 35082384, 2022). "The N-terminal hydrophobic region and BRICHOS domain of GKN1 were sufficient for its tumor-suppressive functions." (PMID 36287119, 2022). "BPN tumor cells normally express high levels of transcripts that mark surface mucous cells in the stomach, such as Muc5ac and Gkn1." (PMID 33821796, 2021). "Several epithelial markers were elevated in RE, Keratin 13, Keratin 20, and Gastrokine-1, relative to other groups, while neoplasia markers desmin and vimentin were elevated in BE and EAC compared to control." (PMID 32650561, 2020). "Within node positive patients, tumor weights in the group with median‐low GKN1 or GKN2 expressions were significantly higher than those in the group with median‐high GKN1 expression, but are independent of pathological T stage." (PMID 31463974, 2020). "In particular, NKX6.3 transcriptional factor was found to bind specifically to the upstream sequences of GKN1, a gastric-specific tumor suppressor, and dramatically increase expression of the latter." (PMID 26314965, 2015). "Although current research focuses on the potential clinical use of GKN1 in the treatment of tumor, little is known about its expression and function in other organ systems or the significance of GKN1 polymorphisms in cancer." (PMID 25999661, 2015). "The TUNEL assay demonstrated that endogenous GKN1 significantly induced apoptosis in AGS cells, and examination of morphology demonstrated that the nuclei of GKN1 transfected tumor cells exhibited condensation and fragmentation." (PMID 22621392, 2012). "The increased levels of GKN1 in gastric cells could protect the mucosa from injury, thereby promoting the repair of injured mucosa and inhibiting tumor growth." (PMID 39524138, 2024). "Furthermore, inoculation of GKN1 + cancer cells in mice significantly hindered tumor progression supporting the role of GKN1 as a tumor suppressor." (PMID 35082384, 2022). "miR-185 is induced by GKN1 and required for GKN1’s tumor-suppressive activities." (PMID 36287119, 2022). "Our in vitro results support the hypothesis that secreted GKN1 protein acts as tumor suppressor by changing the invasive capacity of cancer cells and preventing transdifferentiation of primary acinar cells." (PMID 35082384, 2022). "Interestingly, NKX6.3 dramatically increased the expression of GKN1, a gastric-specific tumor suppressor, at the mRNA level." (PMID 26314965, 2015). "To determine whether the tumor suppressor effect of NKX6.3 is dependent on GKN1, we analyzed cell viability and proliferation in AGSNKX6.3 and MKN1NKX6.3 cells after GKN1 silencing with shGKN1." (PMID 26314965, 2015). "GKN1 expression also enhanced tumor cell sensitivity to 5-FU treatment." (PMID 22621392, 2012). "In addition, GKN1-positive exosomes could inhibit tumor growth in GC mice model, indicating the potential of exosomal GKN1 in the diagnosis of GC." (PMID 35066729, 2023).
tumor (continued). "(C) Violin plots of single-cell sequencing data showing expression levels of Gkn1, Tff1, Tff2, Cym, Pgc, Pga5, and Pou2f3 transcripts in BPN tumor clusters 1–3 and highlighting key drug-mediated cell-identity changes." (PMID 33821796, 2021). "In colorectal and gastric cancers, UBR5 was found to accelerate tumor growth by destabilizing the tumor suppressors ECRG4 and GKN1 following their ubiquitination." (PMID 33777788, 2021). "Gastrokine 1 (GKN1), a gastric tumor suppressor gene, is predominantly expressed in the stomach, which suppresses the carcinogenicity by reducing the cell viability by inhibiting the cell cycle progression and inducing cell apoptosis." (PMID 33050101, 2020). "The second ranked module, M434, represents downregulation of tumor suppressors such as TFF2, GKN1 and GKN2 in gastric mucosal barrier (GMB) homeostasis in GC." (PMID 31463974, 2020). "Our mRNA expression data showing high-level mRNA expression only in primary normal gastric tissue are consistent with a role of GKN1 and GKN2 as a tumor suppressor." (PMID 24460791, 2014). "This suggests that GKN1 and GKN2 function at earlier stages in tumor cell evolution, or in more complex tumor microenvironments." (PMID 24460791, 2014). "Experimental results showed that the exosomal GKN1 inhibited GC growth by binding to HRas and inhibiting its combination with b-raf and c-raf, which then decreased HRas/Raf/MEK/ERK signaling in AGS, MKN1 and xenograft tumor tissues." (PMID 35066729, 2023). "Recent evidence illustrated that GKN1 and GKN2 may play an important role in the preservation of gastric mucosal homeostasis and function as a gastric individual tumor suppressor." (PMID 30774821, 2018). "GKN1 and GKN2 are reported to function as cell growth inhibitors and tumor suppressors in GC." (PMID 24460791, 2014). "We speculate that EBNA1 may have a more pronounced effect on GKN1 and GKN2 expression in situations where EBV may infect primary gastric cells where basal expression of GKN1 and GKN2 are high and important for tumor suppression." (PMID 24460791, 2014). "It is also possible that EBNA1 may regulate GKN1 or GNK2 only in tissue or tumor microenvironments that are not readily recapitulated in cell culture." (PMID 24460791, 2014).
cancer (23 papers, 2009 to 2025). A tumor composed of atypical neoplastic, often pleomorphic cells that invade other tissues. "Moreover, this cancer-related decrease in serum GKN1 was more evident in advanced GC patients than in early GC patients, with GKN1 diagnostic accuracies at the optimum cut-off (0.9675) of 0.8912 and 0.9589 for early GC and advanced GC, respectively." (PMID 38069253, 2023). "In addition, the AUC values for the diagnosis of other cancers based on serum GKN1 protein showed a dissatisfactory diagnostic efficacy (data not shown)." (PMID 31376239, 2019). "As a summary, our study demonstrated that cancer‐derived exosomal GKN1 inhibited proliferation, invasion, while inhibiting the PI3K/AKT/mTOR signaling pathway." (PMID 39524138, 2024). "The aim of the present study was to evaluate the expression of pro‐apoptotic Bax, caspase‐3, and caspase −9, and anti‐apoptotic Bcl‐2 in cancer cells in order to understand the apoptotic pathway induced by GKN1." (PMID 39524138, 2024). "In this study, 27 cancer specimens’ samples were selected to evaluate the altered expression of GKN1 and GKN2 genes." (PMID 30774821, 2018). "Molecularly, the GKN1 protein contains a BRICHOS domain, which is associated with dementia, respiratory distress and cancer." (PMID 22621392, 2012). "The risk factors such as H. pylori can contribute to the down regulation of GKN1; meanwhile induce ulceration and cancer." (PMID 22621392, 2012). "We first performed RT-PCR and immunoblot analysis to detect expression of GKN1 mRNA and protein levels in cancer cell lines and tissue specimens." (PMID 22621392, 2012). "The measurement of GKN1 is primarily utilized for early cancer diagnosis." (PMID 39524138, 2024). "Epidemiological studies indicate that between 1-3% of infected people develop cancer, so the lasting effect of GKN1 expression on the rest of the cancer-free population is unknown." (PMID 36317116, 2022). "Gastrokine 1 cooperated with keratin 14, inhibited anoikis, and promoted cancer metastasis." (PMID 36230714, 2022). "Although loss of GKN1 has been associated with gastric cancer, we observed no increased prevalence of gastric or other cancer in GKN1−/− mice up to 12 months of age (data not shown)." (PMID 33947892, 2021). "The following data of flow cytometry and TUNEL assay showed that GKN1 may induce apoptosis in cancer cells." (PMID 22621392, 2012). "The ubiquitination of GKN1 by UBR5 reduces its stability, leading to diminished GKN1-mediated suppression of cell proliferation and migration, thereby promoting cancer cell growth and metastasis." (PMID 39857943, 2025). "In summary, UBR5 interacts with key proteins such as MOAP-1, MOIP-1, β-catenin, TXNIP, MYC, CDC73, CAPZA1, TIP60, GKN1, and ECRG4, NF-kB, highlighting its pivotal roles in promoting metastasis, therapeutic resistance, and cancer cell survival." (PMID 39857943, 2025). "Accordingly, GKN1+ ECs, MUC1+ ECs, and VIM+ ECs were regarded as cancer cells." (PMID 39422697, 2024). "This was confirmed by PET scans of GKN1−/− mice indicating no cancers present, and by histology of the stomach and other tissues." (PMID 33947892, 2021). "Thus GKN1−/− mice are lean but otherwise healthy with no signs of cancer or inflammation." (PMID 33947892, 2021). "Not surprisingly, similarity among different cancer types was identified in only 6 out of 23 clusters, including E3 (IRS2, KRT6A), E5 (CD24, STMN1), E8 (GKN1, MUC5AC), E9 (PHGR1, TFF3), E10 (TFF3, TPO) and E13 (VTN and ITIH5)." (PMID 36333338, 2022).
infection (4 papers, 2017 to 2026). The state of being infected such as from the introduction of a foreign agent such as serum, vaccine, antigenic substance or organism. "We therefore investigated whether Gkn1 is required to clear AIEC from the gastrointestinal tract by comparing the course of infection in wild-type and Gkn1-deficient (Gkn1-/-) mice." (PMID 41727627, 2026). "In contrast, the expression of Gkn1 and Gkn2 was hardly detectable in non-infected mice and rather increased little for Gkn2 after infection, particularly in Tff1KO mice (data not shown)." (PMID 28604600, 2017).
GKN1 also shares sentences with these, for which no sentence is quoted: chronic gastritis (2 papers); dysplasia (2); hepatocellular carcinoma (2); prostate carcinoma (2); adenocarcinoma (1); adenoma (1); Hepatic steatosis (1); inflammatory bowel disease (1); Insulin resistance (1); intestinal tumors (1); oral mucositis (1); pancreatic cancer (1); respiratory disease (1).